PRRX1 (paired related homeobox 1)
Diseases named in the same sentence as PRRX1 in open-access papers (continued):
Sharing a sentence is not in itself a finding about the gene and the disease.
glioma (9 papers, 2021 to 2024). A benign or malignant brain and spinal cord tumor that arises from glial cells (astrocytes, oligodendrocytes, ependymal cells). "We next examined the effect of PRRX1 knockdown on the expression levels of glioma stem cell markers." (PMID 34214250, 2022). "We found that the expression of paired related homeobox 1 (PRRX1) is induced by BMPs in glioma-initiating cells." (PMID 35693928, 2022). "Consistently, silencing Prrx1 markedly inhibited glioma proliferation, stemness, and angiogenesis in vivo." (PMID 34131109, 2021). "In order to investigate the biological behaviors of Prrx1 in glioma cells, we successfully constructed the Prrx1 overexpressed lentivirus (Prrx1-OE) and two independent Prrx1 shRNA-expression lentivirus (shPrrx1-1 and shPrrx1-2)." (PMID 34131109, 2021). "Consistently, elevated expression of Prrx1 in glioma was also validated in clinical specimens from Zhujiang Hospital." (PMID 34131109, 2021). "High and low Prrx1 expressions were detected in 45 and 27 glioma specimens through IHC staining, respectively." (PMID 34131109, 2021). "Consistently, we observed by immunofluorescence in glioma specimens that tumor regions with high expression of Prrx1 displayed higher vessel density relative to those with low Prrx1 expression." (PMID 34131109, 2021). "We further observed that Prrx1 expression was consistently upregulated across all grades and histologic types of glioma, suggesting the importance of this gene throughout glioma progression." (PMID 34131109, 2021). "In this study, Prrx1 was found to be markedly upregulated in glioma specimens and elevated Prrx1 expression was inversely correlated with prognosis of glioma patients." (PMID 34131109, 2021). "Consistently, we found in glioma cell lines that Prrx1 upregulated the expression and secretion levels of classical proangiogenic factors such as TGF-β1 and VEGF." (PMID 34131109, 2021). "Stable Prrx1-knockdown U87-Luc cell or vehicle cells were orthotopically implanted into nude mice to further confirm the role of Prrx1 in glioma stemness and angiogenesis." (PMID 34131109, 2021). "Using a combination of subcellular proteomics and in vivo analyses, we revealed that Prrx1 potentiates stemness and vessels formation in glioma by activating the TGF-β/smad pathway and upregulating stemness-related genes and proangiogenic factors." (PMID 34131109, 2021). "In the present study, we demonstrated for the first time that Prrx1 functioned as a driving factor for glioma stemness and angiogenesis both in vitro and in vivo." (PMID 34131109, 2021). "In summary, our findings revealed that Prrx1/TGF-β/smad signal axis exerted a critical role in glioma stemness and angiogeneis." (PMID 34131109, 2021). "In conclusion, these findings suggested that Prrx1 plays a critical role in regulating glioma angiogenesis." (PMID 34131109, 2021). "Prrx1 expression was positively correlated with SOX2 positive rate in glioma tissues, with 76.1% and 37% in Prrx1-high and Prrx1-low groups, respectively." (PMID 34131109, 2021). "RT-qPCR and western blot assays were performed to measure the expression of Prrx1 in glioma cell lines." (PMID 34131109, 2021). "Moreover, PRRX1 was shown to promote angiogenesis in gliomas by upregulating the expression of proangiogenic factors such as VEGF." (PMID 35281030, 2022). "To test whether PRRX1 induction is sufficient for loss of stem cell‐like properties in GICs, we examined the effect of ectopic expression of PRRX1 on neurosphere formation and glioma stem cell marker expression." (PMID 34214250, 2022). "Collectively, our study has provided a novel mechanism for GSCs and angiogenesis in gliomas, suggesting that Prrx1 might be a feasible predictive biomarker and a potential therapeutic target for glioma patients." (PMID 34131109, 2021). "Therefore, Prrx1 disruption suppressed glioma progression in vivo and improved the prognosis of mice." (PMID 34131109, 2021).
glioma (continued). "Herein, we demonstrated the critical roles that Prrx1 played in gliomas stemness and angiogenesis." (PMID 34131109, 2021). "To elucidate whether TGF-β/smad pathway is involved in the Prrx1-mediated stemness and angiogenesis in gliomas, we performed rescue experiments using TGF-β1 siRNA and SRI-011381, a TGF-β/smad signaling agonist, in NSTCs and GSCs." (PMID 34131109, 2021). "Besides, clinical data also demonstrated the positive correlation between Prrx1 expression and vessels density in glioma specimens." (PMID 34131109, 2021). "However, little is known about the role of Prrx1 in glioma progression such as stemness acquisition and angiogenesis." (PMID 34131109, 2021). "Prrx1 also promoted glioma angiogenesis by upregulating proangiogenic factors such as VEGF." (PMID 34131109, 2021). "Subsequent to disclosing the essential role Prrx1 played in glioma stemness, we proved that Prrx1 could promote vessels formation both in vitro and in vivo." (PMID 34131109, 2021). "Based on the results of GSEA and western blot analysis, it turned out that Prrx1 could function as a positive regulator of TGF-β/smad pathway in both glioma cells and specimens." (PMID 34131109, 2021). "PRRX1 could potentiate glioma-initiating cells via DRD2-mediated ERK and AKT activation." (PMID 33987093, 2021). "Finally, we performed bioinformatics and IHC analyses to determine whether activation of the Prrx1/TGF-β/smad signal axis along with indicated malignant properties in our glioma cell models was also evident in glioma specimens." (PMID 34131109, 2021). "Therefore, we envision that Prrx1 may serve as a potential target and provide new strategy for glioma therapies." (PMID 34131109, 2021). "Positive correlation between expression of Prrx1 and proangiogenic genes such as VEGF-A was also observed in multiple GEO glioma datasets." (PMID 34131109, 2021). "To identify the oncogenic signaling related to Prrx1, we applied GSEA to glioma specimens from five GEO datasets respectively (GSE4290, GSE4412, GSE7696, GSE8692, and GSE13041)." (PMID 34131109, 2021). "In the present study, we found that Prrx1 could transactivate TGF-β1 expression and activate the TGF-β/smad signaling pathway in gliomas." (PMID 34131109, 2021). "Prrx1 potentiated stemness acquisition of non-stem tumor cells (NSTCs) and stemness maintenance of glioma stem cells (GSCs) by upregulating GSC markers including CD133, SOX2, and OCT4." (PMID 34131109, 2021). "For instance, MES-specific PRRX1 (sufficient to convert ADRN to MES subtypes) was overexpressed in tumour samples compared to matched normal tissue of multiple cancers including low-grade glioma, GBM, DLBCL, STAD, PAAD, and THYM." (PMID 35201514, 2021).
melanoma (9 papers, 2022 to 2025). A malignant, usually aggressive tumor composed of atypical, neoplastic melanocytes. "We detected low PRRX1 expression in nevus but increased levels in primary human melanoma and cell lines carrying the BRAFV600E mutation." (PMID 38978350, 2024). "Conversely, we found that loss of PRRX1 in metastatic samples is an independent prognostic predictor of poor survival for melanoma patients." (PMID 38978350, 2024). "The association of Loxl3 expression with Snail1 and Prrx1 levels seen in primary melanoma-derived cells is reproduced in a collection of established human melanoma cell lines." (PMID 35267510, 2022). "Since we have recently shown that high expression of PRRX1 in melanoma correlates with invasiveness, we were prompted to explore whether the loss of PRRX1 might impact SPARC expression in invasive melanoma cells." (PMID 40943659, 2025). "At the protein level, we were able to confirm the significant downregulation of Snail1 and Prrx1 upon Loxl3 silencing, suggesting that Loxl3 might control Prrx1 and Snail1 expression in BrafV600E-mutated mouse melanoma cells." (PMID 35267510, 2022). "In conclusion, the study highlights the role of the PRRX1/TCF7L2-Sp1/miR-29b1~a signaling axis in regulating SPARC expression in melanoma." (PMID 40943659, 2025). "This decrease in PRRX1 expression was accompanied by lower SPARC levels across all three subcellular fractions of melanoma cells." (PMID 40943659, 2025). "Collectively, these results indicate that PRRX1 acts as a transcriptional activator of the SPARC gene in melanoma cells, promoting its expression." (PMID 40943659, 2025). "Herein, we show that SPARC expression in melanoma cells relies on transcriptional activation by PRRX1/TCF7L2-Sp1 and post-transcriptional regulation by miR-29b1~a." (PMID 40943659, 2025). "Taken together, SPARC expression in melanoma cells relies on transcriptional activation by PRRX1/TCF7L2-Sp1 and is modulated through miR-29b1~a, which provides fine-tuning regulation over the switch between phenotypic states." (PMID 40943659, 2025). "Here, we show that stable depletion of PRRX1 improves the growth of melanoma xenografts and increases the number of distant spontaneous metastases, compared to controls." (PMID 38978350, 2024). "Upon interaction with vascular niches the mesenchymal phenotype of melanoma cells, which is crucially determined by Prrx1, is suppressed and tumor growth is promoted in a hierarchical fashion." (PMID 37179302, 2023). "Their results showed that in melanoma cells PRRX1 was overexpressed, and it was regulated by miR-485-5p." (PMID 36982460, 2023). "In melanoma cells with transfected mirR-485-5p, by measuring luciferase activity it was shown that miR-485-5p repressed PRRX1, which blocked the TGFβ pathway and EMT." (PMID 36982460, 2023). "Complementary in vitro and in vivo studies in mouse melanoma cells confirmed Loxl3’s contribution to melanoma progression and metastasis, in part by modulating phenotypic switching through Snail1 and Prrx1 EMT-TFs." (PMID 35267510, 2022). "Snail1-induced EMT was involved in melanoma metastasis by facilitating immune evasion, while there is limited data linking PRRX1 to melanoma." (PMID 35267510, 2022). "Further experiments are needed in order to understand the mechanisms governing the regulation of LOXL3, SNAIL1, and PRRX1 factors in melanomagenesis and their specific contribution to melanoma cell plasticity." (PMID 35267510, 2022). "However, in contrast to the “MITF-low” GES, melanoma cells with the “EMT” GES showed high expression levels of EMT-TFs (ZEB1, SNAI1, and PRRX1), which have been demonstrated to play a critical role in melanoma progression." (PMID 35884783, 2022). "Indeed, primary melanoma cells showed an upregulation of Mitf and Twist1 and a downregulation of Snai1 and Prrx1 levels upon Loxl3 silencing." (PMID 35267510, 2022).
melanoma (continued). "Indeed, when we analyzed the expression of these genes in a panel of human melanoma cell lines, the majority of cells carrying activated BRAFV600E mutation expressed LOXL3, SNAIL1, and PRRX1 as determined by gene and protein analyses." (PMID 35267510, 2022). "Notably, high LOXL3 and SNAI1 or PRRX1 mRNA levels were significantly associated in human cutaneous melanoma patients, unveiling a previously unknown LOXL3–SNAIL1–PRRX1 axis relevant to melanoma biology." (PMID 35267510, 2022). "In this study, we propose a PRRX1/TCF7L2-Sp1/miR-29 regulatory axis, which involve Wnt/β-catenin and MAPK signaling pathways to regulate SPARC expression in melanoma." (PMID 40943659, 2025). "In conclusion, we propose a PRRX1/TCF7L2-Sp1/miR-29 regulatory axis, which involves Wnt/β-catenin and MAPK signaling pathways, as a key mechanism controlling SPARC expression in melanoma." (PMID 40943659, 2025). "Together, our work suggests that PRRX1 expression, β-catenin/TCFL2, c-Jun, and Sp1 converge to achieve maximal SPARC promoter activity in melanoma cells." (PMID 40943659, 2025). "Given the relevance of PRRX1 in the context of melanoma, we further examined the correlation between the PRRX1 and SPARC expression in two independent sets of our melanoma patients (cohorts I and II)." (PMID 40943659, 2025). "Studies have shown that alterations in melanoma phenotype in mice are partly mediated through the regulation of epithelial-mesenchymal transition transcription factors (EMT-TFs), such as SNAIL1 and PRRX1." (PMID 41250755, 2025). "What's more, LOXL3 could also regulate the metastasis of melanoma via affecting the expression of MITF, TWIST1, SNAIL1 and PRRX1, which were molecules that involved in EMT process." (PMID 36324258, 2022). "Hence, although further research is needed, we speculate that PRRX1 and the activation of β-catenin/TCF7L2 may regulate the maximal activation of the SPARC promoter in melanoma cells, and maybe that of other mesenchymal genes." (PMID 40943659, 2025). "Complementary in vitro and in vivo studies in primary-derived mouse and established human melanoma cell lines confirmed LOXL3 contribution to melanoma progression, in part by modulating melanoma phenotypic plasticity by regulating the expression of SNAIL1 and PRRX1 EMT-TFs." (PMID 35267510, 2022). "Keeping in mind that phenotype switching in melanoma cells entails the exclusive expression of β-catenin cofactors LEF1 or TCF7L2, we interrogated whether SPARC can be integrated into this process, either in the presence or absence of PRRX1 expression." (PMID 40943659, 2025).
neuroblastoma (8 papers, 2019 to 2025). Neuroblastoma (NB) is the most common solid, extracranial childhood tumor. "Next, we detected that MOXD1, as well as the MES-associated PRRX1, SNAI2, and NOTCH2 genes were virtually restricted to the MES-like SH-EP cells by analyzing extracted RNA from five different conventional neuroblastoma cell lines." (PMID 38905335, 2024). "While recent studies have implicated that the PRRX1 super-enhancer TF drives the mesenchymal state, in our hands, genetic knockdown of YAP alone leads to increased expression of adrenergic genes/proteins and decreased mesenchymal proteins in mesenchymal neuroblastoma cells." (PMID 34572875, 2021). "Reciprocally, YAP overexpression in an adrenergic neuroblastoma cell line leads to increase in SNAI2 and PRRX1 with a concomitant decrease in PHOX2B, GATA3, and DBH (data unpublished)." (PMID 34572875, 2021). "Stage 2B neuroblastoma was more heterogeneous in DBH and PHOX2B expression, with all cells lacking expression of PRRX1 and very few cells positive for PDGFRA." (PMID 34493726, 2021). "We assayed markers of both mesenchymal differentiation (VIM, PRRX1 and SNAI1) and adrenergic differentiation (NCAM, NF68), but observed no reproducible changes in gene expression, suggesting that GATA3 knock-down only affects proliferation and death, but not differentiation, in neuroblastoma cells." (PMID 31831790, 2019).
atrial fibrillation (7 papers, 2013 to 2026). A disorder characterized by an electrocardiographic finding of a supraventricular arrhythmia characterized by the replacement of consistent P waves by rapid oscillations or fibrillatory waves that vary in size, shape and timing and are accompanied by an irregular ventricular response. "Given the exploratory nature of the study, the limited sample size, and potential confounding by age, further large-scale studies are required to clarify the role of PRRX1 genetic variants in atrial fibrillation susceptibility." (PMID 41595504, 2026). "In the present study, we observed a higher frequency of the rare G allele and GG genotype of the rs3903239 polymorphism of the PRRX1 gene in patients with atrial fibrillation compared with conditionally healthy controls." (PMID 41595504, 2026). "Several genetic research studies indicated the association of rs3903239, an SNP in the upstream of PRRX1 gene, with atrial fibrillation." (PMID 39567526, 2024). "In this case–control study conducted in a Kazakh population, the rs3903239 polymorphism of the PRRX1 gene showed a non-significant trend toward a higher frequency of the rare G allele among patients with atrial fibrillation." (PMID 41595504, 2026).
head and neck squamous cell carcinoma (7 papers, 2019 to 2025). A squamous cell carcinoma that arises from any of the following anatomic sites: lip and oral cavity, nasal cavity, paranasal sinuses, pharynx, larynx, and salivary glands. "Another gene associated with the maintenance of the dormant phenotype in head and neck squamous cell carcinoma (HNSCC) is the paired-related homeobox transcription factor (PRRX1)." (PMID 36430404, 2022). "In head and neck squamous cell carcinoma cells, PRRX1 has a synergistic effect with the activated TGF-β1 on the promotion of the migration and invasion of cancer cells, and regulates the phenotypic plasticity and dormancy of tumor cells." (PMID 32811812, 2020). "Paired-related homeobox transcription factor (PRRX1) has been associated with the activation of EMT program and in maintaining the dormancy phenotype in head and neck squamous cell carcinoma (HNSCC) patients." (PMID 31817646, 2019). "Furthermore, in a study of head and neck squamous cell carcinoma (HNSCC), the paired-related homeobox transcription factor PRRX1, known for its role as a transcriptional coactivator involved in the EMT, has been implicated in regulating dormancy mechanisms." (PMID 41404065, 2025).